APP (amyloid beta precursor protein)
Diseases named in the same sentence as APP in open-access papers (continued):
Sharing a sentence is not in itself a finding about the gene and the disease.
tumor (continued). "To confirm these in vitro findings further, we examined the effect of APP in the tumor xenograft mouse model." (PMID 25491510, 2014). "In accord, the final tumor weight was significantly higher in A53T α-Syn+/+ mice (149.4±43.2 mg) than APP/PS1+/− (65.1±26.2 mg) or control (B6 genotype) littermates (74.0±20.3 mg)." (PMID 21611169, 2011). "The inhibitory effects on tumor cell proliferation attribute to Aβ in the conditioning media of the cells over-expressing wild type or Swedish mutant APP." (PMID 19480719, 2009). "Cell adhesion/migration, organization of ECM,haemostasis and thrombosis, modulation of APP,tumor suppressor." (PMID 18793429, 2008). "Trajectory analysis uncovered a specific lineage (Lineage 4) driving the normal-to-malignant transition, while cell communication analysis highlighted interactions between malignant cells and tumor-associated macrophages (TAMs) mediated by MIF and APP signaling pathways." (PMID 42089585, 2026). "This could imply a previously unrecognized role of APP in tumor biology or immune modulation in GBM26–29." (PMID 40595248, 2025). "The sex-specific responses to AOM/DSS treatment, particularly the increased tumor burden in male AppNL-G-F mice compared to females, might be influenced by differences in inflammatory responses and APP-mediated pathways." (PMID 41279101, 2025). "Accordingly, this study investigates how APP protein accumulation in GBM correlates with large-scale transcriptional changes, aiming to uncover pathway-level associations that may influence tumor progression." (PMID 41003874, 2025). "This may be due to the increased tumor vascular density, where endothelial cells upregulate APP expression in response to hypoxic microenvironment and pro-angiogenic signals, such as HIF-1α and VEGF." (PMID 41561750, 2025). "Furthermore, the binding of DR6 to its ligand APP (amyloid precursor protein) promotes endothelial cell death and tumor cell extravasation." (PMID 40868135, 2025). "WB and IHC analyses proved higher APP protein levels in tumor bulk compared to adjacent tissues." (PMID 41561750, 2025). "The differential expression of immune markers, specifically M1 and M2 macrophage markers in APP mutant mice, suggests a unique immune environment that may contribute to the sex-specific tumor outcomes observed." (PMID 41279101, 2025). "In contrast, knocking down APP inhibited tumour growth in vivo and in vitro." (PMID 41614805, 2025). "APP signaling transmits inhibitory signals that suppress the phagocytic activity of tumor-associated macrophages (TAMs) and reduces immune activity within the TME, allowing tumor cells to evade immune surveillance and promote tumor progression." (PMID 40260248, 2025). "Thus, GOLIM4-dependent secretion activated an APP-dependent autocrine loop that drove tumor progression." (PMID 38662435, 2024). "Similarly, tumor-cell-derived amyloid precursor protein (APP) can activate the RIPK1-RIPK3-MLKL axis-induced necroptosis through binding to death receptor 6 (DR6) in endothelial cells, which enhances the extravasation of circulating tumor cells (CTCs)." (PMID 39337436, 2024). "Interestingly, the interaction with the highest probability was observed in the tumor → non-tumor direction for the APP → CD74 interaction." (PMID 39095793, 2024). "Interestingly, we found distinct patterns of APP accumulation, which is a direct precursor protein to Abeta, and which was present in tumor-adjacent neurons and axonal spheroids accentuated around areas of tumor necrosis." (PMID 39220249, 2024). "However, according to the single‐cell data, the high levels of APP expression in macrophages in the tumour state are indicated." (PMID 38445803, 2024). "Additionally, SERPINA5 had differential expression in normal and metastatic tissues, while APP as well as OLR1 had differential expression in tumor and metastatic tissues (P < 0.05)." (PMID 39012409, 2024).
tumor (continued). "Furthermore, we elucidated the role of APP in regulating of tumour protection and prevention of tumour progression, serving as important prognostic markers and indicators in ccRCC cohorts." (PMID 38445803, 2024). "Ligand APP from tumor cells and fibroblasts might increase the expression of SELENOP in macrophages." (PMID 38044943, 2023). "Moreover, patients with a low APP gene expression and a high tumor junction burden showed a worse prognosis compared to patients with high APP score and high tumor junction burden when treated with ICIs." (PMID 36776840, 2023). "The hub genes, including PIK3R1, CTNNB1, JUN, EGFR, and APP, might play an important role in tumor development." (PMID 35733630, 2022). "In addition, the presence of APP itself was assessed in the same tumor tissues in general as well as in tumor blood vessels." (PMID 34592066, 2022). "The binding of amyloid precursor protein (APP) to death receptor 6 (DR6) eased the necrosis (necroptosis) pathway, and knocking down either APP or DR6 results in a considerable reduction of tumor cell (TC)-induced necroptosis and TCs transendothelial migration." (PMID 36476230, 2022). "Furthermore, the APP intracellular domain can interact with adaptor proteins to activate downstream signaling molecules, thereby affecting the metastasis of tumor cells." (PMID 36157221, 2022). "Except EGCG, studies have shown that also other HDACis (such as VPA) could downregulate the levels of APP, leading to decreased tumor growth, invasion and angiogenesis." (PMID 37305348, 2022). "However, APP is up-regulated in BC cells and tissues, which promotes tumor formation and progression." (PMID 34685653, 2021). "Besides APP and APLP, another amyloidogenic protein such as α-synuclein (SNCA) and transthyretin (TTR) is reported to an association with tumorigenesis and tumor growth." (PMID 34066808, 2021). "Collectively, this study demonstrates the feasibility of exploiting DR6/APP interaction to regulate hematogenous tumor cells transendothelial migration and provides PEG‐tAHP‐DRI as a novel and promising inhibitor of DR6/APP interaction for developments of anti‐hematogenous metastatic therapies." (PMID 34105277, 2021). "Another study also suggested that the tumor promoter role of APP may be obtained by modulating the expression of metalloproteinase and EMT‐related genes (Miyazaki, Ikeda, Horie‐Inoue, & Inoue, 2014)." (PMID 31304688, 2019). "In this study, we first indicate that the role of EGCG in APP and ADAM10 regulation is mediated by HuR, result in tumour cells apoptosis via HuR‐Erk1/2‐APP/ADAM10 pathway, adding a new dimension to EGCG‐mediated regulation of APP and ADAM10 in cancer cell apoptosis." (PMID 30793483, 2019). "Notably, mesotrypsin produced by tumor cells acts to cleave the Kunitz protease inhibitor domain of the soluble, secreted APP ectodomain, which likely contributes to the procoagulant character of the tumor microenvironment." (PMID 26840089, 2016). "Upregulation of AP2α and positive correlation between APP and AP2α in tumor tissue." (PMID 26840089, 2016). "Nevertheless, the precise mechanism of APP on tumor cells still remains to be disclosed." (PMID 27694936, 2016). "The control MDA-MB-231 cells showed higher tumor growth than APP-kd cells." (PMID 25491510, 2014). "Tumor growth was negligible and difficult to measure in APP-kd group up to 22-days." (PMID 25491510, 2014). "To investigate whether naturally secreted Aβ has any effects on tumor cell proliferation, we have taken advantage of the APP over-expressing cells that generate high levels of Aβ." (PMID 19480719, 2009). "Thus, we concluded that high APP level in GC endothelial cells may contribute to tumor immune suppression and evasion via the PD-1/PD-L1 pathway by promoting PD-1 expression in macrophages." (PMID 41561750, 2025).
tumor (continued). "Because frequently mutated genes in tumor tissues may have a much greater effect on patients’ survival than SNPs in the same genes, we further investigated the mutation status of PANX1 and APP in liver tumor tissues using the public database of the cBioPortal for Cancer Genomics." (PMID 39090420, 2025). "Amyloid precursor protein (APP), which reported to play an important role in intracellular signaling, synaptic and neuronal plasticity, and cell adhesion, was found to be significantly upregulated in malignant regions, indicating its association with the invasion of tumor cells." (PMID 41147013, 2025). "Furthermore, disulfidptosis activity also showed tight correlations with tumors at scRNA‐seq, and pairs, such as MIF_CD74_CD44, MIF_CD74_CXCR4, MDK_NCL, and APP_CD74, might be potential targets in disulfidptosis‐related tumor microenvironment." (PMID 38420162, 2024). "In particular, considering that the impact of tumor junction burdens seemed to be modulated by APP, Kosari and collegues hypothesized that the neo-antingenic potential of chromosomal rearrangements was dependent on the capability of cancer cells to present neoantigens to the immune system." (PMID 36776840, 2023). "Therefore, if prospectively confirmed, this interaction signature between the tumor junction burdens and APP gene sets could represent a potential biomarker for immunotherapies patients’ selection in clinical practice." (PMID 36776840, 2023). "Notch receptor is the second Presenilin1 substrate identified after APP, it is cleaved by Presenilin1 and releases into the cytoplasm its intracellular domain, which is a well-known transcription factor for several genes, mostly involved in tumor cell survival and differentiation." (PMID 34781973, 2021). "The rhythmic expression of miR-34a was observed in the tumor cell lines and its overexpression contributes to abnormal expression of the clock genes Per1 and Per2, as well as the specific genes involved in memory formation, amyloid precursor protein (APP) metabolism and tau phosphorylation states." (PMID 33089205, 2020). "Accordingly, APP may play dual roles in tumor progression and act as an antioncogene in KIRC." (PMID 32328125, 2020). "The interaction between bone metastatic BC tumor cells and MMP19+ TAMs was mediated by the amyloid precursor protein (APP) signaling pathway." (PMID 41362730, 2026). "In the ccRCC dataset, macrophages demonstrated robust signaling capabilities within the tumor microenvironment, engaging in various pathways including COLLAGEN, APP, and CD96." (PMID 41488617, 2025). "Tumor-adjacent cortex was immunohistochemically stained for b-A4, t-AT8, NeuN, APP, Ki67, and Iba1, and cells were quantified using Matlab and QuPath script." (PMID 40351831, 2025). "Inhibition or knockdown of APP and ADAM10 reduced proliferation, supporting their roles in tumor progression." (PMID 41614805, 2025). "Following treatment with anlotinib combined with aPD-L1 or aPD-1, APP signaling was further diminished, while interactions between CD8+ T cells and tumor cells increased." (PMID 40260248, 2025). "Subsequently, we examined the ligand-receptor pairs of these signals, noting that ligands such as MIF, MDK, and APP are highly expressed on C0 RPS4Y1+ tumor cells and are instrumental in mediating communication with other tumor microenvironments." (PMID 40230840, 2025). "Our study identified four critical DEGs (CXCL8, PSMC2, APP, and SLC20A1) that demonstrated high performance in identifying CRC in diverse populations and ethnicities, covering a range of tumor stages and histologic grades." (PMID 38243058, 2024). "Expression of CCL28, APP, EHF and LINC00342, among others, is increased in LP cells relative to the basal tumor." (PMID 39478117, 2024). "Concurrently, some signaling pathways related to tumor proliferation and progression, such as NOTCH, APP, and CEACAM, were also significantly activated in the high-lipid metabolism group." (PMID 38685045, 2024).
tumor (continued). "Among that, the protein expression of IGF2BP3, B2M, CD36, CDKN1A, ANKRD33B, and LHFPL2 were up-regulated; However, the protein expression of APP and CTDSPL was low in both normal and tumor tissues." (PMID 39470474, 2024). "Silencing APP also downregulated MTT-based viability, whereas it significantly suppressed PCOLCE/CALR-induced tumor inhibition." (PMID 36943734, 2023). "Therefore, to test whether there was an interaction between APP gene sets and tumor junction burdens that affected outcomes, they selected 12 APP gene sets from the Gene Ontology Biological Processes data set in the Molecular Signature Database and calculated their enrichment scores." (PMID 36776840, 2023). "The results showed that CAFs, tumor cells, and B cells can participate in a series of functional interactions involving CXCL12 receptor-mediated APP, COPA, and MIF signaling." (PMID 37719863, 2023). "Some studies have found that the dysregulation of Amyloid Precursor Protein (APP) expression, which contains an extracellular copper-binding domain at the N-terminal end, is also involved in the development of EMT in tumor cells." (PMID 36419894, 2022). "In particular, the BACE1/2 dependent maturation of amyloidogenic proteins such as APP or PMEL, has been shown to affect TME cells behavior and to act both in paracrine and autocrine way driving tumor proliferation and progression." (PMID 33926496, 2021). "In this study, we designed and constructed a size variable nanodrug delivery system with high photothermal conversion efficiency and good anti-tumour effect based on AuNRs and UCST polymers: AuNRs-DOX/mPEG10K-peptide/P(AAm-co-AN) (APP-DOX)." (PMID 34630113, 2021). "APP-DOX had a suitable size and can be targeted to accumulate in tumour tissues through circulation in the body." (PMID 34630113, 2021). "Binding of amyloid precursor protein (APP) and death receptor 6 (DR6) is shown to initiate the necroptosis pathway and lead to tumor cells metastasis." (PMID 34105277, 2021). "In our results, we found that APP and its binding partner TNFRSF21 were also highly expressed in tumor-related B-cells." (PMID 33777800, 2021). "The results of qPCR experiment performed in HNSCC tissues suggested that APP and COL1A2 were significantly upregulated in HNSCC tissues when compared to adjacent matched tissues, implying the potential tumor promoter role of them in HNSCC progression." (PMID 31304688, 2019). "To evaluate the role of HuR in the regulation of APP and ADAM10 by EGCG, we overexpressed HuR in tumour cells." (PMID 30793483, 2019). "The facts that deregulation in PS1 can induce chromosome miss-segregation and tumour generation, and both PS1 and APP associate with centrosomes, suggest that in addition to Aβ generation, expression of PS1 in APP transgenic mice may affect cell cycle deregulation and therefore APP phosphorylation." (PMID 22112898, 2011). "The significant downregulation of APP and the obvious decrease of MHC-I score may lead to immune escape of tumor cells in C3, resulting in patients in C3 having a relatively poor prognosis." (PMID 41001011, 2025). "Given that the APP‒TNFRSF21 axis mediates tumor cell-induced endothelial necroptosis, we inferred that APP+ epithelial cells might induce necroptosis of FOLR2+ macrophages via the APP‒TNFRSF21 axis." (PMID 39702278, 2024). "It decreased with increasing tumor cell infiltration (P < .0001) and was independent of frequent expression of APP in neuronal cell bodies (N = 182/205) and in tumor necrosis-related axonal spheroids (N = 195/205; P = .46)." (PMID 39220249, 2024). "Interestingly, we found that the expression of MLKL and APP in BUC was positively correlated with immune cell infiltration, but negatively correlated with tumor stemness." (PMID 37000317, 2023). "The interaction between APP and DR6 provides a new target for anti-hematogenous tumor metastases." (PMID 36836481, 2023). "APP and COPA are suggested to play promoting roles in tumor progression and metastasis." (PMID 37945567, 2023).
tumor (continued). "The compound of APP and death receptor 6 (DR6/TNFRSF21) inhibited the activation of necroptosis of vascular endothelial cells, resulting in significant reduction in transdermal migration of tumor cells, thus controlling tumor metastasis." (PMID 35237304, 2022). "Moreover, this study also found that binding of DR6 to its ligand amyloid precursor protein (APP) led to necroptotic endothelial cell death and tumor cells metastasis and extravasation." (PMID 36361505, 2022). "The ex vivo autoradiography images demonstrated much higher [18F]F-DPA uptake in irradiated and non-irradiated FaDu tumours compared to brain from an APP/PS1-21 transgenic mouse." (PMID 33340054, 2021). "Having demonstrated that NETosis can be modulated by the β-secretases activity on APP, they wondered how this process influences tumor growth and observed that inhibiting BACE1/2 in skin tumor bearing mice results in a strong reduction of tumor volume." (PMID 33926496, 2021). "Given that ADAM10 is the primary α-secretase responsible for non-amyloidogenic APP cleavage, understanding how androgen signalling influences this pathway could reveal novel mechanisms of tumour progression." (PMID 41614805, 2025). "Heterogeneous vascular endothelial cellscan secrete molecules such as MIF and APP, which act on macrophagesurface molecules or complexes such as CD74 and CD44, inhibiting macrophagepolarization toward the antitumor M1 phenotype and promoting polarizationtoward the pro-tumor M2 phenotype." (PMID 40834268, 2025). "The observed effects of Rapamycin on tumor suppression are likely to involve the autophagy process, evidenced by the inhibition of autophagy modulators (TGFβ1, RGS19 and AKT1), autophagosome biogenesis components (AMBRA1, ATG9B and TMEM74) and autophagy byproducts (APP)." (PMID 38276004, 2024). "Moreover, qRT-PCR verified seven apoptosis-related genes (APP, DOCK8, IFI44, MDK, SLC27A2, TNFAIP2, WNT5A) with at least 2 fold changes by means of 2−ΔΔCt method, finding that APP, SLC27A2 and WNT5A had a low expression, while DOCK8, IFI44, MDK, TNFAIP2 had a high expression in ccRCC tumor tissues." (PMID 33748185, 2021). "Hence, our study revealed a significant correlation between a high risk score and immunosuppression and its association with the growth and differentiation of B and T cells, and high expression of PLAU, APP and EGFR were the main factors of tumor immunosuppression." (PMID 33232279, 2020). "Furthermore, six tumor progression genes (GNAI2, ODC1, APP, TNFRSF12A, BASP1, and LARP6) and nine migration and metastasis‐related genes (MSN, FLOT1, LAMB3, MYL9, ITGB1, FTH1, TPM4, and PMEPA1), which could explain the invasive characteristics of SCC, were identified." (PMID 40776410, 2025). "The binding of amyloid precursor protein (APP) expressed on tumor cells to death receptor 6 (DR6) could initiate the necroptosis pathway, which leads to necroptotic cell death of vascular endothelial cells (ECs) and results in tumor cells (TCs) extravasation and metastasis." (PMID 34105277, 2021). "All pRMS tumor clusters use the MIF-CD74 pathway to suppress the immune response, while APP, PTN, and CXCL12 signaling are employed predominantly by the non-myogenic tumor clusters." (PMID 41373578, 2025). "In contrast, transcriptomic data of pretreatment tumor tissues showed no significant enrichment of either IFN or APP signatures, suggesting that antitumor immunity is locally disturbed in the TME to support tumor progression." (PMID 34843570, 2021).